HLA-DRB1 (major histocompatibility complex, class II, DR beta 1)
Diseases named in the same sentence as HLA-DRB1 in open-access papers (continued):
Sharing a sentence is not in itself a finding about the gene and the disease.
type 2 diabetes (12 papers, 2006 to 2025). "HLA-DRB1 was proved to increase insulin secretion and reduce the risk of type 2 diabetes." (PMID 31881887, 2019). "Moreover, it is unlikely that HLA-DRB1 could play any role in discriminating MODY from type 2 diabetes." (PMID 28052112, 2017). "The study reported by Williams found lower expression of the HLA-DRB1 mRNA in type 2 diabetes, which was consistent with our findings, and suggests that HLA-DRB1 is protective for type 2 diabetes by increasing insulin secretion." (PMID 32455133, 2020). "The incidence of HLA-DRB1* 1501 was found to be significant in type 2 diabetes and non-diabetic, particularly ASO-positive patients, compared to control subjects." (PMID 16611256, 2006). "The incidence of HLA-DRB1*1501 was found to be significant in type 2 diabetes and non-diabetic ASO-positive patients compared with controls, and the frequency of this allele was significant in patients with ASO." (PMID 16611256, 2006). "Finally, we note the unexpectedly high frequency of the protective HLA-DRB1*15 haplotypes in our African American cases compared with Europeans, does not indicate inclusion of non-autoimmune Type 1 diabetes or cases with Type 2 diabetes." (PMID 23398374, 2013).
inflammatory bowel disease (11 papers, 2010 to 2025). A spectrum of small and large bowel inflammatory diseases of unknown etiology. "Nominal associations were also seen between AAU and previously AS-associated allele HLA-DRB1*0103,38 which is also known to be associated with inflammatory bowel disease." (PMID 32492107, 2020). "In patients with both PSC and inflammatory bowel disease, PSC is also associated with HLA-DRB1*13 but only with individuals with IBD." (PMID 32793226, 2020).
Obesity (11 papers, 2019 to 2025). Accumulation of substantial excess body fat. "There is also evidence to suggest obesity interacts with individual genetic factors to increase susceptibility to MS, and significant interaction has been observed between HLA-DRB1*15 allele presence and obesity, in relation to risk of MS." (PMID 36457996, 2022). "Deleting the HLA-DRB1*11 allele is associated with obesity/overweight, which is a risk for cancer development." (PMID 34712820, 2021). "In our study, deletion of the HLA-DRB1*11 allele was associated (beneficial effect) with obesity/overweight (OR = 0.13; 95% CI [0.01–1.14]; and p = 0.03)." (PMID 34712820, 2021). "The pathogenesis of the disease is complex, including genetic susceptibility (Human leucocyte antigen DRB1 allele (HLA-DRB1) and shared epitope), epigenetic modifications and environmental factors (psychologic stress, smoking, obesity, microbiota...)." (PMID 31952247, 2020). "Notably, HLA‐DRB1*15 has been shown to interact with environmental risk factors such as smoking and obesity, influencing disease onset and severity." (PMID 38659387, 2024). "However, deletion of the HLA-DRB1*11 allele is associated (beneficial effect) with obesity/overweight (OR = 0.13; 95% CI [0.01–1.14]; and p = 0.03)." (PMID 34712820, 2021). "The risk factors for RA include genetics (especially inheritance of HLA-DRB1*01 and HLA-DRB1*04), female sex, obesity, smoking, and silica exposure." (PMID 40806618, 2025). "Using Swedish population-based case-control studies (5,460 cases and 7,275 controls), we assessed MS risk in relation to interactions between overweight/obesity at age 20 years, IM history, EBNA-1 levels, and HLA-DRB1*15:01 status by calculating ORs with 95% CIs using logistic regression." (PMID 33465039, 2021). "Furthermore, 3-way interactions were present between HLA-DRB1*15:01, overweight/obesity at age 20 years, and each aspect of EBV infection." (PMID 33465039, 2021). "HLA-DRB1 amino acids, haplotypes, or haplotype groups associated with RA susceptibility are also associated with CV mortality and this association is independent of sex, hypertension and obesity." (PMID 35468805, 2022). "Differential gene expression revealed that genes associated with innate immune responses (LYZ), antigen processing and presentation (HLA-DRB1, HLA-DRB5, IFI30), as well as cell signaling and migration (VIM, RGS1, NCF) were upregulated in the HBC subset with pregravid obesity." (PMID 39872537, 2024). "Among them, the site and the route of injection, older age, obesity, renal failure, immunodeficiency and certain HLA types, particularly homozygosity for HLA-DRB1 * 0301 and HLA-DRB1 * 0701, have been associated with lack of immunogenicity." (PMID 31505743, 2019). "Additionally, interactive effects have been shown between HLA-DRB1*15:01 and obesity: individuals classed as obese who carry HLA-DRB1*15 but not HLA-A*02 have an OR of 16.2 (95% CI 7.5, 35.2) for developing MS." (PMID 34088990, 2021).
thyroid disease (11 papers, 2010 to 2025). "They showed that HLA-DRB1*04:10 was a risk allele for moyamoya disease and that thyroid diseases, such as Graves’ and Hashimoto’s disease, were more common in HLA-DRB1*04:10-positive patients with moyamoya disease than in HLA-DRB1*04:10-negative patients." (PMID 32928146, 2020). "When analyzing the relationship between the HLA-DRB1 genotypes and AITD, HT, and BGD, a strong association of the thyroid pathology with the *03/*16 genotype was observed." (PMID 38672712, 2024). "HLA-DRB1 * 04:10 is a risk allele for MMD, and it is also associated with thyroid diseases in MMD patients." (PMID 37900127, 2023). "Therefore, this significant interaction between HLA-DRB1*0301 genotype and H. pylori infection supports the role of simultaneous genetic and environmental factors in sustaining the thyroid disease in children." (PMID 35799701, 2022). "Genetically, HLA (HLADRB1) and non-HLA genes (JACK/STAT – PTPN22) seem to be involved in IBD and thyroiditis common pathways." (PMID 39968296, 2025).
myositis (10 papers, 2006 to 2025). "However, the HLA-DQA1*03:03 allele was a unique risk factor for MAV in Caucasians (OR=3.87, 95% CI=1.56-9.54, p=0.002), while the known myositis risk factor, HLA-DRB1*03:01, was a protective factor for MAV (OR=0.41, 95% CI=0,18-0.94, p= 0.033)." (PMID 40895572, 2025). "Complement C4 or C3 protein or C4P/G, HLA-DRB1*03 and/or HLA-DRB1*15, C4A deficiency or C4A GCN range of variations were risk factors for various myositis-related autoantibodies except for MSA in general." (PMID 36171069, 2023). "The relative roles of HLA-DRB1*03 and C4A deficiency on genetic risk of IIM, and how the C4 GCN variations and complement protein levels correlated with the presence of myositis-related autoantibodies were also examined." (PMID 36171069, 2023). "Of these genes, one had a higher expression in HLA-DRB1*03-positive patients with myositis, and seven had a higher expression in HLA-DRB1*03-negative patients with myositis." (PMID 30157932, 2018). "PI4KAP1 was found to have a higher expression in CD4+ T cells of HLA-DRB1*03-positive patients with myositis, and TRGC2, CTSW, HPCAL4, ZNF683, and GOLGA8B were found to have a higher expression in CD4+ T cells of HLA-DRB1*03-negative patients with myositis." (PMID 30157932, 2018). "Six genes were differentially expressed in CD4+ T cells of HLA-DRB1*03-positive compared with HLA-DRB1*03-negative myositis patients." (PMID 30157932, 2018). "Previous studies also showed an association between HLA-DRB1 0803 with the development of SS, SLE, SSc, PM, and idiopathic inflammatory myopathy (i.e., PM, DM, or myositis overlapping with other collagen vascular disease)." (PMID 30048527, 2018). "The frequency of HLA-DRB1*07 was significantly higher among myositis patients with dysphagia than among controls (p = 0.01; pcorr NS; OR = 4.78; 95% CI: 1.03–24.42)." (PMID 24894810, 2014). "The novel identification of the HLA-DQA1*03:03 allele as a unique risk factor for MAV and the protective factor of HLA-DRB1*03:01 suggests the role of a genetic predisposition in the MAV group that differs from non-MAV myositis patients." (PMID 40895572, 2025). "Interestingly, we found that ZNF683 also had a higher expression in CD8+ T cells of HLA-DRB1*03-negative myositis patients when comparing PM and DM, suggesting that the expression of ZNF683 is common for both subpopulations of T cells." (PMID 30157932, 2018). "The HLA-DRB1*0301 and HLA-DQA1*0501 alleles have been reported as risk factors for myositis in Western populations, whereas DRB1*0803 may increase PM susceptibility among the Japanese population." (PMID 24894810, 2014). "A genetic study found that HLA-DRB1*11:01 is associated with a higher risk of anti-HMGCR IMNM in both white American and African American adult populations, whereas HLA-DRB1*07:01 seem to be associated with a risk of anti-HMGCR myositis in small series of children." (PMID 28871260, 2017). "Comparison of HLA-DRB1*12 allele frequencies between myositis patients with and without ILD showed a similar trend of being higher among those with ILD than among those without, although the difference between the two groups was not statistically significant (p = 0.35; OR = 1.59; 95% CI: 0.63–4.00)." (PMID 24894810, 2014). "HLA-DRB1 and DQA1 genotypes of 17 patients with myositis-SSc overlap and 69 healthy individuals were determined using commercial sequence-specific oligonucleotide kits." (PMID 35547355, 2022). "We found that PI4KAP1 had a higher expression in CD4+ T cells of HLA-DRB1*03-positive myositis and that TRGC2, CTSW, HPCAL4, ZNF683, and GOLGA8B had a higher expression in CD4+ T cells of HLA-DRB1*03-negative myositis patients." (PMID 30157932, 2018). "Among these, five genes had a higher expression in CD4+ T cells from HLA-DRB1*03-positive patients with myositis, and eight genes had a higher expression in CD4+ T cells from HLA-DRB1*03-negative patients with myositis." (PMID 30157932, 2018).
myositis (continued). "In adult myositis, gene–environment interactions have been found between HLA-DRB1*03, smoking and the presence of anti-Jo-1 autoantibodies, and between HLA-DRB1*11:01 and anti-3-hydroxy-3-methylglutaryl-CoA reductase (anti-HMGCR)-positive statin-induced immune-mediated necrotising myopathy." (PMID 35094092, 2022). "This resulted in eight genes that were differentially expressed between HLA-DRB1*03-positive and -negative myositis (FDR < 0.05)." (PMID 30157932, 2018). "At the second analytical stage, we found that although HLA-DRB1*03-positive and -negative myositis are not separated by the first PCs, 12 genes were differentially expressed in CD4+ T cells in comparison of myositis patients with different genotypes." (PMID 30157932, 2018). "The gene expression pattern in HLA-DRB1*03-positive and -negative myositis was examined by PCA, but the first PCs did not separate HLA-DRB1*03-positive from HLA-DRB1*03-negative myositis patients, suggesting that these patients are similar on a high genomic level." (PMID 30157932, 2018). "Therefore, we searched for differentially expressed genes between HLA-DRB1*03-positive and -negative myositis patients in CD4+ T cells." (PMID 30157932, 2018). "HLA-DRB1*03, DQA1*05 and DQB1*02 were therefore removed from the data, and the overall exact tests recalculated, after which no further overall differences were detected between myositis subtype versus controls." (PMID 16507114, 2006).
tuberculosis (10 papers, 2012 to 2025). A chronic, recurrent infection caused by the bacterium Mycobacterium tuberculosis. "The present work reports the most frequent HLA-DRB1 alleles in the populations ofBrazil, Russia, India, China, and South Africa, which we propose as targets for thedevelopment of new vaccines against tuberculosis." (PMID 34320128, 2021). "A meta-analysis showed that five variants (HLA-DRB1*04, *09, *10, *15, and *16) increase the risk of tuberculosis, especially in East Asian populations, whereas HLA-DRB1*11 is protective." (PMID 28449694, 2017). "Intriguingly, individuals positive for HLA-DRB1*15:01 are known to be susceptible to both MS and tuberculosis." (PMID 22435930, 2012). "A meta-analysis of HLA-DRB1 alleles and risk of tuberculosis (TB) in Asian patients found HLA-DRB1*07:01 associated with protection from TB." (PMID 32776973, 2020). "One SNP position in LD with non-DRB3, non-DRB5 haplotypes (i.e. the ones not linked with HLA-DRB1*04 allelic group, for instance) has been reported to be associated with a positive tuberculosis test in a recent study using genome-wide data paired with fine-mapping of the HLA region." (PMID 32094421, 2020). "In humans as well, where TB has been a leading cause of death for centuries, individual single sequence variants between HLA-DQA1 and HLA-DRB1 have been strongly and repeatedly associated with M. tuberculosis infections and pulmonary TB disease in Icelandic, Russian and Croatian populations." (PMID 40855227, 2025).
autism (9 papers, 2011 to 2022). Persistent deficits in social interaction and communication and interaction as well as a markedly restricted repertoire of activity and interest as well as repetitive patterns of behavior. "Additionally, patients with autism were discovered to have a significantly higher frequency of HLA-DRB1*11 allele than controls." (PMID 31293459, 2019). "It has been reported that there were significant associations between HLA-DRB1*03 and HLA-DRB1*11 variants and autism among Saudi cases." (PMID 33712060, 2021).
pancreatitis (9 papers, 2017 to 2025). Inflammation of the pancreas. "However, 12% of cases carried rs71542416 but were negative for HLA-DRB1∗10:01, suggesting that the SNP may be a tag for other rare HLA alleles, which is consistent with the hypothesis of Heap et al21 who showed an association between HLA-DQA1-HLA-DRB1 variants and thiopurine-induced pancreatitis." (PMID 33058932, 2021).
Parkinson disease (9 papers, 2012 to 2025). A progressive degenerative disorder of the central nervous system characterized by loss of dopamine producing neurons in the substantia nigra and the presence of Lewy bodies in the substantia nigra and locus coeruleus. "Frequencies of HLA-DRB1 phenotypes and alleles in patients with Parkinson’s disease (PD) and healthy controls." (PMID 23139797, 2012). "In conclusion, our study indicated that HLA-DRB1 alleles are associated with sporadic PD in a Chinese Han population, further research will be required to explore the role of HLA-DRB1 alleles in the pathogenesis of Parkinson’ disease." (PMID 23139797, 2012). "In Parkinson’s disease (PD), the neuroprotective effects of smoking have been well established, attributed to mechanisms such as reduced immune activation and the alpha-synuclein interactions mediated by HLA-DRB1, where individuals lacking protective HLA-DRB1 AA alleles exhibit a reduced PD risk." (PMID 39997032, 2025). "Our own work has shown that HLA-DRB1∗04:01 is protective in Parkinson disease (MIM: 168600), while HLA-DRB1∗04:03 is not, as part of a pattern related to the HLA-DRB1 “shared epitope” (SE)." (PMID 40049169, 2025).
vasculitis (9 papers, 2005 to 2026). "“Double dose” HLA-DRB1*04 SE genotypes were found to modestly increase the risk of vasculitis (OR 2.44) and the overall risk of extra-articular RA (OR 1.79)." (PMID 32370106, 2020). "In conclusion, we found that HLA–DRB1 genotypes previously associated with vasculitis and extraarticular disease in RA were associated with premature death in patients with IP." (PMID 18240242, 2008). "In a recent meta-analysis of HLA-DRB1 genotyping studies of patients with RA-associated vasculitis conducted by Gorman and coworkers, vasculitis was found to be associated with the genotypes 0401/0401, 0401/0404, and 0401/0101." (PMID 16277691, 2005). "Double dose HLA-DRB1*04 SE genotypes are associated with a modestly increased risk for vasculitis and other ExRA manifestations." (PMID 16277691, 2005). "The presence of two HLA-DRB1*04 SE alleles was significantly associated with ExRA overall (OR 1.79, 95% CI 1.04–3.08), Felty's syndrome (OR 2.63, 95% CI 1.04–6.63), and vasculitis (OR 2.44, 95% CI 1.22–4.89) compared with patients with RA who lacked these manifestations." (PMID 16277691, 2005). "The high prevalence of vasculitis in patients with Felty's syndrome observed in the present study is consistent with the literature, and may in part be due to shared genetic factors such as HLA-DRB1*04 alleles." (PMID 16277691, 2005). "A study on RA-related vasculitis in Brazil identified that HLA-DRB1*1402 and HLA-DRB1*0101 alleles may offer protection against skin lesions in affected individuals." (PMID 40236704, 2025). "Notably, HLA-DRB1*15 has also been reported as a risk factor for PR3-ANCA associated vasculitis in African Americans, and HLA-DRB1*04 has been associated with several vasculitis." (PMID 34679434, 2021).
Hepatitis (8 papers, 2010 to 2025). Inflammation of the liver. "In total, 25 out of 27 (92.6%) samples from patients with hepatitis were positive for at least one copy of the HLA-DRB1*04:01 allele compared with 10 out of 64 (15.6%) of samples from controls." (PMID 36996873, 2023). "Eight of the 9 cases carried the HLA-DRB1*04:01 gene variant, suggesting a possible variance in immune response being related to novel hepatitis." (PMID 36255724, 2022). "HLA-DRB1*12 association with AIH in patients triggered by hepatitis A needs further studies." (PMID 21067577, 2010). "HLA-DRB1 04:01 has been reported in pediatric patients with AAV2-induced hepatitis in the United Kingdom." (PMID 40079016, 2025). "The patient’s HLA-DRB1 genotype was 04:01, which is consistent with the result of a previously-reported case of childhood hepatitis involving AAV2." (PMID 40079016, 2025). "The presence of HLA-DRB1 04:01 is consistent with that reported in pediatric patients with AAV2 hepatitis in the United Kingdom, indicating that it may have been involved in the host immune response and acute hepatitis in this child." (PMID 40079016, 2025). "This was a single case report, and the possibility that the HLA-DRB1 04:01 genotype was incidentally detected in a host with hepatitis caused by AV2 cannot be ruled out." (PMID 40079016, 2025). "In this study, of the 27 cases of hepatitis with AAV2 infection in children, 25 (93%) had the HLA-DRB1 04:01 genotype." (PMID 40079016, 2025).
myasthenia gravis (8 papers, 2012 to 2025). Myasthenia gravis (MG) is a rare, clinically heterogeneous, autoimmune disorder of the neuromuscular junction characterized by fatigable weakness of voluntary muscles. "Another study presents that lncRNA IFNG-AS1 promotes CD4+ T cell activation and Th1/Treg cell proliferation via regulating HLA-DRB1 in myasthenia gravis." (PMID 32547537, 2020).